NLRP3 (NLR family pyrin domain containing 3)
Diseases named in the same sentence as NLRP3 in open-access papers (continued):
Sharing a sentence is not in itself a finding about the gene and the disease.
infection (continued). "In addition, TLR4 activates NLRP3 inflammatory bodies through a non-classical pathway by recognizing extracellular LPS, which is pivotal in the host defense against pathogen infection and the regulation of inflammatory responses." (PMID 36838365, 2023). "The internalization of the parasites after 2 h of infection was not affected by the deficiency of GSDMD, NLRP3, or Caspase-1/11, but macrophages lacking any of these genes were more susceptible to intracellular replication of the parasite as observed after 48 h and 72 h of infection." (PMID 36828815, 2023). "Our viral titer assays suggest the possible participation of NLRP3 during replication of the NADL cp-BVDV strain, since there was a decrease in the viral titer of the supernatant of the macrophages treated with the CRID3 inhibitor prior to infection with the NADL cp-BVDV strain." (PMID 37515181, 2023). "The lack of effect of NLRP3 and Caspase 1/11 on host cell death during infections with ply+lytA+ strain A66 was unexpected, however receptor redundancy in macrophage death pathways may contribute to the lack of effect of the single knock-outs." (PMID 36897919, 2023). "It should be noted that NLRP3 inflammasome activation in other pathogen infections may not depend on ZBP1, such as the vesicular stomatitis virus." (PMID 36845112, 2023). "In addition to NLRP3-derived IL-1β and IL-18, HMPV infection also leads to the over-expression of TNF and IL-6, which can worsen lung inflammation and disease outcomes following infection." (PMID 37508374, 2023). "Second, the activation of NLRP3 signaling in podocytes resembles inflammaging, a process defined as a chronic, low-grade sterile inflammation with advancing age in the absence of overt infection." (PMID 37487005, 2023). "Moreover, corticosteroids alleviate LPS‐induced inflammation and lung injury by blocking the activation of NLRP3 inflammasome, highlighting that NLRP3 inflammasome can be a drug target for COPD treatment and involves the pathogenesis of COPD, particularly those induced by infection." (PMID 37904708, 2023). "Moreover, Nlrc4-/- and Nlrp3-/- macrophages presented similar impaired responses to T. cruzi, underscoring the non-redundant roles played by these inflammasomes during infection." (PMID 38124741, 2023). "During host cell infection with DENV, first, signal 1 is activated: cytoplasmic pattern recognition receptors sense DENV viral RNA and trigger the NF-κB signaling pathway, thereby upregulating the transcription of pro-caspase-1, the NLRP3 inflammasome, pro-IL-1β, and pro-IL-18." (PMID 38249297, 2023). "For example, the administration of a NLRP3 inhibitor during the early stages (the first five days post infection) of IAV infection can be detrimental, while it proves beneficial in the later stages (the period from the seventh day to the ninth day after infection)." (PMID 37376638, 2023). "For the first time, the importance of NLRP3 inflammasome activation in a bovine lung infection has been demonstrated, whereas GOS mitigated the infection-induced inflammatory response, which might be explained by the inhibition of the NLRP3 inflammasome activation." (PMID 35777914, 2022). "Caspase-1 and NLRP3 inhibitors blocked inflammasomes in vitro but did not impact macrophage infection, measured as mNG+ macrophage frequency, and reduced the inflammatory response to infection." (PMID 35483404, 2022). "Our data showed that ECHO 11 infection or LPS/Nigericin treatment induced pro-IL-1β maturation, and CASP-1/GSDMD cleavages in THP-1 cells, and these activations were remarkably attenuated by knocking down either one of the NLRP3 inflammasome components and pyroptosis." (PMID 36026486, 2022). "For instance, upon infection of differentiated human nasal epithelial cells (hNECs) and primary human nasal epithelial progenitor cells with human rhinovirus (HRVs), the epithelial NLRP3 inflammasomes mediated the hNEC pyroptosis via DDX33/DDX58–NLRP3–caspase-1–GSDMD axis." (PMID 35806033, 2022).
infection (continued). "In the absence of infection, the NLRP3 inflammasome is a key mediator of sterile inflammation and is activated in response to injury and disease through stimuli that include glycaemic injury, oxidative stress, and the release of danger-associated molecular patterns (DAMPs), e.g., ATP." (PMID 35755447, 2022). "Furthermore, IL-6 production was not significantly different in both wild-type and Nlrp3-/- BMDMs following ΔpknF mutant infection when compared to wild-type Mtb or complemented mutant strains." (PMID 34324582, 2021). "Furthermore, to address the effect of FMDV on NLRP3 inflammasome-mediated IL-1β production, we found that IL-1β secretion and protein maturation were impaired in PK-15 cells expressing shNLRP3 (short hairpin NLRP3, shNLRP3) after FMDV infection compared with control cells." (PMID 35062226, 2021). "In this article, we summarized the preclinical and clinical evidence on the participation of NLRP3 activation in HSCT with an emphasis on the role of excessive inflammasome activation in the development of transplant complications including GvHD, TRM, severe infections, and disease relapse." (PMID 34769275, 2021). "Furthermore, the expression of NLRP3 and AIM2 was comparably induced by U112 and XWK4 infection." (PMID 34869331, 2021). "In addition, OLT1177 reduced cytokine release in mononuclear cells isolated from patients with CAPS, in which constitutive active mutants of NLRP3 spontaneously release IL-1β and IL-18 in the absence of tissue damage or infection." (PMID 33673188, 2021). "Thus, we conclude that in our oral infection model, NLRP3 and Caspase-11 are not involved in the control of S. Tm dissemination from the gut lumen during the first day of infection." (PMID 31953493, 2020). "Currently, it has been found that the mechanisms against infection of nonsuperficial fungi may be related to the NLRP3 inflammasome." (PMID 32148650, 2020). "Furthermore, the absence of Asc, Nlrp3/Aim2 or Casp1/11 had no impact on cell death upon infection with strains of M. tuberculosis, indicating that M. tuberculosis-induced cell death is inflammasome-independent." (PMID 32111888, 2020). "It is widely accepted that, as activators of the Nlrp3 inflammasome, DAMPs are involved in producing “sterile inflammation,” which is seen in tissues in stress situations and in tissue/organ damage in the absence of infection-related PAMPs." (PMID 32313108, 2020). "Likewise, to determine whether DENV-2 activates the NLRP3 inflammasome, cell lysates from DENV-2 infected HMEC-1 cells were analyzed by western blot at different infection times using specific anti-NLRP3 antibody." (PMID 32210961, 2020). "Treatment with the phagocytosis inhibitor cytochalasin D during infection with Mtb only partially inhibited ASC-speck formation after 24 h, despite strong inhibition of Mtb uptake, supporting the conclusion that Mtb also can activate the NLRP3 inflammasome through PM damage from outside of the cell." (PMID 32385301, 2020). "Infection with Gram-negative bacteria from the Enterobacteriaceae family, such as Salmonella typhimurium, Escherichia coli, and Citrobacter rodentium, activate the NLRP3 inflammasome." (PMID 32582195, 2020). "We found significantly higher percentage of NLRP3 expressing dendritic cells and macrophages, higher production of IL-1β and higher expression of NLRP3 and ASC in the livers of Gal-3+/+ mice early after infection with N. aromaticivorans in comparison with the group of Gal-3−/− mice." (PMID 32707678, 2020). "At 3 and 6 hours post infection, MAYV induced increased expression of Casp1, Nlrp3, Aim2 and Asc." (PMID 31479495, 2019). "Infection of human corneal epithelial cells with virulent HSV-1 laboratory strains (McKrae or 17) or with the clinical isolate KOS79 induced a significant early expression of NLRP3 and IFI16 inflammasomes, compared to a steady level of control β-actin (P < 0.05)." (PMID 31367214, 2019).
infection (continued). "Taken together, our results suggest that NLRP3 inflammasome activation by MAYV impacts the pathogenesis of an acute in vivo model of infection but does not play a role in viral control in macrophages or in vivo." (PMID 31479495, 2019). "Additionally, lack of NLRP3 promoted host antihelminth effector mechanisms and other type 2 immune responses, but was detrimental with respect to infection-induced tissue damage." (PMID 31586037, 2019). "After VSV or EMCV infection, despite NLRP3 inflammasome activation, cell death was not affected in NLRP3, ASC, or caspase-1-deficient BMDMs or after treatment with a broad caspase inhibitor like zVAD-fmk, suggesting that pyroptotic or apoptotic cell death was not involved." (PMID 31024004, 2019). "Furthermore, NLRP3 inflammasome inhibition was found to decrease IL-6 and IFN-γ levels in BAL from BALB/c mice but only IFN-γ levels in the case of C57BL/6 mice on day 5 post-infection." (PMID 30964929, 2019). "Finally, caspase inhibition did not affect ASC speck formation and ASC oligomerization after infection, indicating that the NLRP3 inflammasome formation and activation is independent of any caspase activity." (PMID 31024004, 2019). "Although most Gbps are known to target invading pathogens, Gbp5 can also assemble the NLRP3 inflammasome in the absence of infection, and within infected cells, such assembly could conceivably take place on or near the pathogen vacuole." (PMID 30154263, 2018). "However, infection with type I (GT1) or type III (CTG) strain parasites was able to induce IL-1β release from LPS-treated cells, indicating that infection can activate the NLRP3 inflammasome in cells that have previously been primed." (PMID 30154263, 2018). "Therefore, in our study, the production of IFN-γ was reduced in serum but was not altered at the initial infection site of Nlrp3−/−, Asc−/−, and Caspase-1/11−/− mice when compared with WT mice during N. caninum infection." (PMID 30105037, 2018). "However, T3SS-negative P. aeruginosa activated the non-canonical NLRP3 inflammasome during long term infection." (PMID 30062052, 2018). "Murine studies identified NLRP3 inflammasome activity as the primary driver of AT-induced tissue damage and mortality, however, the mechanisms through which NLRP3 inflammasome activity promotes infection are not fully defined." (PMID 29490278, 2018). "The activation of NLRP3 inflammasome appears in response to infection and is amplified by danger signals triggered during the infection, or by tissue injury or alterations in tissue homeostasis without infection." (PMID 28191008, 2017). "However, the role of the NLRP3 protein itself appeared to be dependent on the inoculating dose of IAV, as NLRP3 deficiency did not impact mortality when a low dose of IAV was used, but did lead to worse survival after infection with higher doses." (PMID 28740490, 2017). "Interestingly, levels of IL-1β and IL-18 in the lung are markedly reduced in Nlrp3-/- mice with slower kinetics over the initial 6 days of infection with LVS or SchuS4 infection, but are not completely ablated." (PMID 27926940, 2016). "Although NLRP3 is activated by a wide variety of pathogens including bacteria, viruses, protozoa and fungi, it does not appear to be critical for host defense for many infections in vivo." (PMID 27551512, 2016). "In addition, with the exception of a few studies, the roles played by Nlrp3, Aim2 or other inflammasomes during infection with Ft LVS and SchuS4 have not been investigated." (PMID 27926940, 2016). "Interestingly, ΔYopM infection in BMDMs failed to upregulate NLRP3 and HMGB1 secretion, but significantly induced caspase-1 activation and IL-1β secretion." (PMID 27929533, 2016). "By using co-infection experiments, we determine that the infection of macrophages with C. burnetii inhibits the caspase-11-mediated non-canonical activation of the NLRP3 inflammasome induced by subsequent infection with Escherichia coli or Legionella pneumophila." (PMID 26687278, 2015).
infection (continued). "When cells are not pretreated with ATP, infection with P. gingivalis in this model does not trigger the activation of the NLRP3 inflammasome complex, including NLRP3, ASC and caspase-1, until P. gingivalis LPS stimulation, even though in a short time 2 h (except caspase-1)." (PMID 26511096, 2015). "In our experimental system, NLRP3-NF-κB activation could be detected only during early stages of infection, probably because NF-κB is primarily activated through the TLR pathway at later stages of infection." (PMID 25761061, 2015). "Infection of A/E pathogens, such as EPEC and EHEC, might activate NLRC4 and NLRP3 inflammasomes." (PMID 26332984, 2015). "The NLRP3 inflammasome is known to be triggered by infection with A/E pathogens and shows a non-redundant role in caspase-1 activation when mouse macrophages (mBMDM) are challenged with Citrobacter rodentium, a mouse A/E pathogen possessing the nleA homologous gene." (PMID 26332984, 2015). "Therefore, much like the pathways described for Mtb, if inflammasome-independent IL-1α can be generated during infection, adaptive immunity should be minimally impacted in the absence of NLRP3, ASC, or caspase-1." (PMID 24409181, 2013). "As disordered viral protein aggregates may be formed during infection with a range of different pathogens, our PR8 PB1-F2 NLRP3 inflammasome activation model may serve as a new tool to investigate interactions between pathogenic infections and host immune responses." (PMID 23737748, 2013). "Deletion of the NLRP3 inflammasome did not restrict macrophage infiltration to the site of infection; however the Nlrp3−/− macrophages were unable to control C. rodentium colonization, leading to increases in bacterial loads in the lamina propria and translocation into the mucosa." (PMID 24312491, 2013). "However, unlike the MyD88−/− and IFN-γ−/− mice, which succumbed to infection, the NLRP3−/− and caspase-1−/− mice survived infection." (PMID 24098823, 2013). "Studying the role of inflammasomes in murine infection models revealed critical roles for ASC and caspase-1 in the host defense against S. aureus and V. cholerae, whereas NLRP3 was surprisingly dispensable, even though these pathogens selectively trigger NLRP3 in vitro." (PMID 23666718, 2013). "Western blot analysis reaffirmed that peritoneal macrophages from WT but not Nlrp3−/− mice secreted mature IL-1β to cell supernatants after infection with C. rodentium, and as well, that administration of exogenous IL-1β induced maturation of the cytokine in uninfected WT macrophages." (PMID 24312491, 2013). "Our findings indicate that compensation of IL-1β in mice lacking the NLRP3 inflammasome may promote the clearance of C. rodentium by stimulating inflammatory macrophages in the early stages of infection." (PMID 24312491, 2013). "The redistribution of NLRP3 after EMCV infection was not inhibited by yVAD-CHO." (PMID 22916014, 2012). "Current models of NLRP3 activation indicate it does not act as a traditional receptor but rather as a nexus for different pathways invoked following cellular injury and/or infection, which may also be true for the NLRC4 inflammasome." (PMID 22174673, 2011). "Nlrp3−/− mice had a modest but statistically significantly increase in IL-6 and TNF-α cytokines at 2 weeks (p = 0.026 and p = 0.028, respectively) and 5 weeks post-infection (p = 0.004, p = 0.001, respectively), but all differences were diminished by 16 weeks post-infection." (PMID 20808838, 2010). "Several Nod-like receptor (NLR) family genes (nucleotide-binding oligomerization domain (NOD) 1, NOD2, NLRP2, NLRP3 and class II trans-activator (CIITA)) which act as intracellular sensors to detect cytosolic microbial components and "danger" signals were elevated upon infection." (PMID 21110886, 2010).
infection (continued). "Although not all studies directly measured DAMP levels, discussions highlighted the role of inflammasome activation in neonatal immune dysregulation, suggesting that aberrant NLRP3 signaling may guide uncontrolled inflammation and cell injury even in the absence of infection." (PMID 40806937, 2025). "During natural infection, the sand fly is transmitting salivary and gut products that also activate inflammasomes, thus in addition to NLRP1, other inflammasomes such as NLRP3 may be triggered in neutrophils following infection with L. mexicana in natural settings." (PMID 39250503, 2024). "In addition to by-stander injury elicited in helminthic experimental infections, the presence of NLRP3 modulates disease outcomes as gauged by increased resistance in mouse lacking NLRP3 infected with nematodes such as Trichuris muris and Nippostrongylus brasiliensis." (PMID 38842647, 2024). "Interestingly, we found that NLRP3 expression level increased 24 hours after SARS-CoV-2 infection in phorbol-12-myristate-13-acetate (PMA) - differentiated human THP1 macrophages with different multiplicities of infection (MOI) or at different time points after infection with a MOI of 0.2." (PMID 37920468, 2023). "However, this non-specific broad inhibition of NLRP3 inflammasome activity may disrupt innate immune mechanisms and increase the chances of infection in patients." (PMID 37891975, 2023). "The relative expression levels of the necrotic factors Caspase-1, Caspase-3, NLRP3, and IL-1β proteins in placental nourishing cells were higher in patients with multiple genital tract infections compared to those with single infections or no infections in the PROM group (P < .05)." (PMID 38115314, 2023). "However, in late infection, SVV may reduced caspase-1 expression because 3Cpro cleave NLRP3." (PMID 35958608, 2022). "Accumulating evidence emphasizes the role of the NLRP3 inflammasome in mediating the proinflammatory response to IAV infection as well as the importance of the relationship between beneficial and detrimental activation in determining whether infection will resolve or lapse into hyperinflammation." (PMID 35739522, 2022). "Interestingly, we detected an upregulation of Il1b for both GAS mono-infection and superinfection, which suggests that the incapacity of co-infected macrophages to process and secrete IL-1β is due to a failure in the GAS-inducible activation of the NLRP3 inflammasome." (PMID 36365071, 2022). "Furthermore, compared with the HPI− group, the NLRP3 positive cell rate in the HPI+ group were significantly higher (P < 0.01) at 0.5, 6 and 9 h after infection, the caspase-1 positive cell rate in the HPI+ group were significantly higher (P < 0.01) at 3 and 6 h after infection." (PMID 33678162, 2021). "At this early time point post infection (30 min), neither Mtb nor the ΔpknF mutant alone induced any significant secretion of IL-1β These results suggest that in mouse macrophages, PknF plays an important role in inhibiting the activation of the NLRP3 inflammasome." (PMID 34324582, 2021). "Interestingly, infection of BMDCs with influenza A virus (IAV) was sensed by Nucleotide‐binding oligomerisation domain‐containing protein 2 (NOD2) and RIPK2 and promoted mitophagy, which in turn cleared damaged mitochondria to avoid overactivation of NLRP3 inflammasome." (PMID 34337844, 2021). "However, NLRP3 activation can also occur in the absence of infection." (PMID 32883606, 2020). "However, NLRP3 inflammasome signaling does not clear staphylococci from the lungs of infected mice given that WT and Nlrp3−/− mice had similar bacterial burdens following S. aureus intratracheal infection." (PMID 32231665, 2020). "Interestingly, NLRP3 expression in HUVECs was notably inhibited at the mRNA and protein levels following treatment with a miR‐223‐3p mimic in either the presence or absence of an rTp17 infection." (PMID 33145937, 2020).